PRMT9 (protein arginine methyltransferase 9)
Description:
Arginine methyltransferase that can both catalyze the formation of omega-N monomethylarginine (MMA) and symmetrical dimethylarginine (sDMA). Specifically mediates the symmetrical dimethylation of SF3B2. Involved in the regulation of alternative splicing of pre-mRNA.
Synonyms: PRMT10; FLJ46629
Tractability: Small molecule: a structure with a bound ligand is known. PROTAC: ubiquitination databases record sites on it; its protein half-life has been measured.
Target class: Enzyme; Transferase
Chemical probes: MRK-990 (high quality)
Gene: Protein-coding gene on chromosome 4 (147,635,654 to 147,684,163, reverse strand). Ensembl gene ENSG00000164169.
Subcellular location: Cytoplasm
Subcellular location (Human Protein Atlas): Microtubules; Cytosol; Nucleoplasm
Gene Ontology:
Molecular function: protein binding; protein-arginine N-methyltransferase activity; protein-arginine omega-N symmetric methyltransferase activity; protein methyltransferase activity
Biological process: mRNA processing
Cellular component: cytoplasm
Genetic constraint (gnomAD): Loss-of-function variants: 49 observed, 68.31 expected, observed/expected ratio (o/e) 0.72, 90% interval 0.57 to 0.91. The upper end of that interval is the gene's LOEUF score, 0.91, which puts it in group 3 of 6, group 1 being the genes least tolerant of losing a copy. Missense variants: 851 observed, 967.72 expected, observed/expected ratio (o/e) 0.88, 90% interval 0.83 to 0.93. Synonymous variants: 299 observed, 337.9 expected, observed/expected ratio (o/e) 0.88, 90% interval 0.8 to 0.97.
Homologues: Orthologues: chimpanzee PRMT9 (98% identical), macaque PRMT9 (97% identical), dog PRMT9 (91% identical), pig PRMT9 (90% identical), rabbit PRMT9 (90% identical), guinea pig PRMT9 (89% identical), mouse Prmt9 (87% identical), rat Prmt9 (86% identical), tropical clawed frog prmt9 (60% identical), zebrafish prmt9 (56% identical), Caenorhabditis elegans prmt-9 (17% identical), Drosophila melanogaster Art2 (9% identical). Paralogues in human: PRMT7 (19% identical), CARM1 (12% identical), PRMT3 (12% identical), PRMT2 (11% identical), PRMT1 (10% identical), PRMT8 (10% identical), PRMT6 (9% identical).